XIST (X inactive specific transcript)
Diseases named in the same sentence as XIST in open-access papers (continued):
Sharing a sentence is not in itself a finding about the gene and the disease.
atrial fibrillation (2 papers, 2023). A disorder characterized by an electrocardiographic finding of a supraventricular arrhythmia characterized by the replacement of consistent P waves by rapid oscillations or fibrillatory waves that vary in size, shape and timing and are accompanied by an irregular ventricular response. "Overexpression of lncRNA XIST in EVs derived from adipose tissue MSCs reduced myocardial pyroptosis and inflammation in atrial fibrillation mouse models and atrial myocytes." (PMID 37759491, 2023). "In addition, X-inactive specific transcript (XIST), a type of lncRNA, was transfected into EVs derived from mouse adipose tissue-derived mesenchymal stem cells (AMSCs) and then injected into an atrial fibrillation mouse model." (PMID 36577860, 2023). "They suggested that XIST may blunt myocardial pyroptosis by absorbing miRNA-214-3p to promote Arl2 expression, providing encouraging insight into XIST-based targeted therapy for atrial fibrillation." (PMID 36577860, 2023).
endometrial cancer (2 papers, 2014 to 2025). Primary or metastatic malignant neoplasm involving the endometrium (mucous membrane that lines the endometrial cavity). "qRT-PCR also confirmed that XIST was down-regulated in four of six endometrial cancer samples in our study." (PMID 25286960, 2014). "Although the mechanisms underlying XIST down-regulation and the biological significance of DNA methylation loss remain to be determined, we hypothesize that repressed XIST expression and DNA demethylation might contribute to the aggressive behavior in endometrial cancer, especially in UPSC." (PMID 25286960, 2014).
endometriosis (2 papers, 2022). The growth of functional endometrial tissue in anatomic sites outside the uterine body. "Although some studies have been carried out on the regulation mechanism of NEAT1 and XIST in endometriosis, it still needs to be fully explored in the future, especially in the lncRNA-miRNA-mRNA network." (PMID 36532015, 2022). "In the construction of a ceRNA network composed of four target genes, we found that NEAT1 and XIST have the highest degree of binding to miRNA and may regulate the expression of four genes in endometriosis." (PMID 36532015, 2022). "NEAT1 and XIST may regulate the expression of four TFs (AEBP1, HOXB6, RORB, and KLF2) through the lncRNA-miRNA-mRNA network and participate in the development of endometriosis." (PMID 36532015, 2022).
endothelial dysfunction (2 papers, 2024 to 2025). In vascular diseases, endothelial dysfunction is a systemic pathological state of the endothelium (the inner lining of blood vessels) and can be broadly defined as an imbalance between vasodilating and vasoconstricting substances produced by (or acting on) the endothelium. "Finally, XIST, involved in X-linked silencing via epigenetic regulation, is upregulated in LS and plays a role in oxidative stress response, inflammation, and endothelial dysfunction." (PMID 39408800, 2024). "Finally, XIST, involved in X-linked silencing via epigenetic regulation, is upregulated in LS and plays a role in the oxidative stress response, inflammation, and regulation of endothelial dysfunction." (PMID 39408800, 2024). "XIST promotes cardiovascular disease progression by regulating endothelial dysfunction, inflammation and oxidative stress." (PMID 40342975, 2025). "XIST also plays a role in the oxidative stress response, inflammation, and regulating endothelial dysfunction." (PMID 39408800, 2024).
gestational diabetes (2 papers, 2022 to 2023). Carbohydrate intolerance first diagnosed during pregnancy. "Li’s study showed XIST was downregulated in gestational diabetes mellitus (GDM) and could serve as a diagnostic biomarker." (PMID 35938169, 2022). "Although there is no study to confirm that phytochemicals may suppress XIST expression, one study reports that the expression of XIST correlates directly with the blood glucose levels in gestational diabetes mellitus." (PMID 37571393, 2023).
glomerular nephritis (2 papers, 2019 to 2022). "In addition, XIST levels are significantly elevated in the urine of MN mouse model and in patients with glomerulonephritis (including MN), and XIST concentrations in the urine are positively correlated with the severity of MN." (PMID 35529848, 2022). "Elevated XIST, which could be induced by LPS, is correlated with glomerular nephritis." (PMID 31658856, 2019).
Hyperglycemia (2 papers, 2021 to 2022). An increased concentration of glucose in the blood. "Another lncRNA XIST regulates hyperglycemia-associated apoptosis and migration in human retinal pigment epithelial cells." (PMID 34707685, 2021).
hypertrophic cardiomyopathy (2 papers, 2024 to 2025). A condition in which the myocardium is hypertrophied without an obvious cause. "In cardiomyocytes, distinct genes such as TMTC1, ART3, ARHGAP24, SHROOM3, and XIST were linked to dilated cardiomyopathy, Neo-Hypoplastic Left Heart Syndrome, hypertrophic cardiomyopathy, HF-Hypoplastic Left Heart Syndrome, and Tetralogy of Fallot, respectively." (PMID 39202774, 2024). "The specific role of ARL15 (ADP Ribosylation Factor Like GTPase 15, 604699) in dilated cardiomyopathy prediction, XIST (X Inactive Specific Transcript) for hypertrophic cardiomyopathy, and hypoplastic left heart syndrome has been validated." (PMID 39202774, 2024). "The up-regulation of XIST in hypertrophic cardiomyopathy has also been predicted by other methods like LightGBM and CatBoost and functionally validated by several publications." (PMID 39202774, 2024).
idiopathic pulmonary fibrosis (2 papers, 2017 to 2025). Idiopathic pulmonary fibrosis (IPF) is a nonneoplastic pulmonary disease that is characterized by the formation of scar tissue within the lungs in the absence of any known cause. "In the present study, we investigated the hypothesis that XIST play a promotive role in bleomycin (BLM)-induced ECM and pulmonary fibrosis; XIST exerts its effect through miR-139 regulation." (PMID 29029436, 2017). "However, there are few reports about the functional and mechanistic effect of XIST on pulmonary fibroblasts proliferation and pulmonary fibrosis." (PMID 29029436, 2017). "Taken together, we revealed the promotive effect of XIST on BLM-induced PF, and demonstrated the mechanism by which XIST/miR-139 axis exerts its effect on regulating pulmonary fibrosis, providing a potential therapy to treat PF." (PMID 29029436, 2017). "In conclusion, we revealed the promotive effect of XIST on BLM-induced PF, and demonstrated the mechanism by which XIST exerts its effect on promoting human and mouse fibroblast proliferation, ECM protein expression and pulmonary fibrosis." (PMID 29029436, 2017).
kidney stone (2 papers, 2022 to 2024). "XIST was found to interact with miR-223-3p and the NLRP3/Caspase-1/IL-1β pathway, thereby modulating inflammatory responses, ROS production, and kidney stone development." (PMID 38397450, 2024).
lymphoma (2 papers, 2021 to 2022). A malignant (clonal) proliferation of B- lymphocytes or T- lymphocytes which involves the lymph nodes, bone marrow and/or extranodal sites. "In Oncomine, compared to normal tissues, XIST expression was obviously lower in several cancers, such as BRCA, COAD, LUAD, lymphoma and OV." (PMID 36212008, 2022).
mastitis (2 papers, 2019 to 2021). Inflammation of breast tissue during lactation or postpartum due to an obstructed duct or infection. "So, the function of XIST in bovine mastitis was to inhibit this excessive and sustained inflammatory process." (PMID 30362186, 2019). "This study aimed to investigate whether XIST played a critical role in regulating the inflammatory response to pathogenic stimulus through NF‐κB pathway and further identify the relationship between NF‐κB pathway and NLRP3 inflammasome in bovine mastitis." (PMID 30362186, 2019). "In the cell model of bovine S. aureus mastitis, the S. aureus adhesion to epithelial cells can be mediated by lncRNAs TUB and H19, and the NF-κB/NLRP3 inflammasome pathway is regulated by the lncRNA XIST." (PMID 34895356, 2021).
mental disorder (2 papers, 2021 to 2025). A disease that has its basis in the disruption of mental process. "In addition, we found XIST as another key lncRNA in the ceRNA network, which is associated with mental disorders." (PMID 34952924, 2021).
metabolic syndrome (2 papers, 2023 to 2024). A cluster of metabolic risk factors for CARDIOVASCULAR DISEASES and TYPE 2 DIABETES MELLITUS. "Finally, this work demonstrated that lncRNA XIST alleviates hepatic IR via regulating the miR‐182‐5p/IGF‐1R axis, which could be the promising therapeutic target of IR‐related diseases such as T2D and metabolic syndrome." (PMID 38018594, 2023).
myelodysplastic syndrome (2 papers, 2017 to 2018). A clonal hematopoietic disorder characterized by dysplasia and ineffective hematopoiesis in one or more of the hematopoietic cell lines. "XIST loss in female mice leads to a highly aggressive myeloproliferative neoplasm and myelodysplastic syndrome (mixed MPN/MDS)." (PMID 30116729, 2018).
oral cancer (2 papers, 2021 to 2022). "A previous study found that oral cancer tissue showed loss of heterozygosity of the X-linked lncRNA XIST gene." (PMID 34640640, 2021). "We suggest that XIST may play an important role in oral cancer morbidity when associated with sex." (PMID 34640640, 2021). "XIST, as a molecular sponge, plays important role in oral cancer by regulating miRNA and competitively binding with target mRNA." (PMID 36035993, 2022). "This suggested that XIST can potentially be an important target for the diagnosis and treatment of oral cancer." (PMID 36035993, 2022). "XIST is an important initiator of X chromosome inactivation and a gene regulator like other lncRNAs in many cancers, including oral cancer." (PMID 36035993, 2022). "Results from this study demonstrated that XIST inhibited apoptosis, and promoted cell proliferation, invasion, and migration to promote the growth of oral cancer." (PMID 36035993, 2022). "This suggested that many lncRNAs, especially XIST, are abnormally expressed in a variety of cancers, including oral cancer, and play a key role in their pathogenesis via the regulation of different pathways." (PMID 36035993, 2022). "Studies found that targeted regulation of the expression of XIST in oral cancer, and some other cancers can inhibit the occurrence and development of tumors." (PMID 36035993, 2022). "The role of XIST in oral cancer has been investigated, and the potential mechanism has been elaborated." (PMID 36035993, 2022). "Here, we provide a brief overview of the role of many kinds of lncRNAs, including XIST, which provides a theoretical basis for the study of the role of XIST in oral cancer." (PMID 36035993, 2022). "This indicated that the abnormal expression of XIST is closely related to the occurrence, development, and treatment of oral cancer." (PMID 36035993, 2022). "Research carried out by our group has shown that cucurbitacin B effectively inhibited the proliferation of oral cancer and significantly reduced the expression of XIST in oral cancer cells." (PMID 36035993, 2022). "The abnormal expression of XIST has been observed in human oral cancer, and it has been found that XIST plays a major role in the pathogenesis of oral cancer." (PMID 36035993, 2022). "To summarize, studying the mechanism and signal pathway of XIST in other cancer cells may provide a theoretical foundation for the future study of XIST in oral cancer." (PMID 36035993, 2022). "To summarize, XIST is abnormally expressed in a variety of cancers, including oral cancer." (PMID 36035993, 2022). "In addition, possible methods, such as RNA-seq and fluorescence in situ hybridization (FISH) assay, can be performed to determine the expression of XIST to provide a potential implication in oral cancer." (PMID 36035993, 2022). "An abnormal expression of XIST is seen in a variety of cancers, including oral cancer." (PMID 36035993, 2022). "The expression pattern of lncRNA XIST is particularly important in oral carcinoma." (PMID 36035993, 2022). "Similarly, studies have shown that knocking down the expression level of XIST can significantly inhibit the proliferation and promote the apoptosis of oral cancer cells." (PMID 36035993, 2022). "XIST can regulate the progression of oral cancer via multiple mechanisms." (PMID 36035993, 2022). "Therefore, XIST can be a potential new target for the treatment of oral cancer." (PMID 36035993, 2022). "Moreover, XIST can increase the drug resistance of cancer cells; this may seriously increase the difficulty of chemotherapy treatment for oral cancer." (PMID 36035993, 2022).
papillary thyroid cancer (2 papers, 2022 to 2024). "Previously, XIST has been reported to promote oncogenic activity in papillary thyroid carcinomas." (PMID 39134413, 2024). "In addition, XIST could also facilitate the migration and invasion of papillary thyroid cancer cells." (PMID 35899235, 2022).
periodontitis (2 papers, 2022 to 2024). An acute or chronic inflammatory process that affects the tissues that surround and support the teeth. "Xu et al32 also described the regulatory role of the XIST/USF2/WDR72 axis in the development of periodontitis." (PMID 39105315, 2024).
preeclampsia (2 papers, 2023). Preeclampsia is a hypertensive disorder of pregnancy that is characterized by new-onset hypertension with proteinuria presenting after 20 weeks of gestation, and depending on mild or severe forms may initially present with severe headache, visual disturbances, and hyperreflexia. "In comparison to normal pregnant placental tissues, the expression of lncRNA XIST was found to be considerably reduced in the placentas of Preeclampsia patients." (PMID 37745705, 2023). "lncRNA XIST is involved in the development of Preeclampsia by regulating the proliferation and invasive ability of trophoblast HTR-8/SVneo through miR-135b." (PMID 37745705, 2023).
pulmonary arterial hypertension (2 papers, 2021 to 2024). Pulmonary arterial hypertension (PAH) is a group of diseases characterized by mean pulmonary artery pressure >20 mmHg and elevated pulmonary arterial resistance leading to right heart failure. "This may be of importance in the context of pulmonary hypertension given the known role of HIF-1α in pulmonary hypertension but to date this action of XIST has only been reported in colonic cancer cells." (PMID 34068984, 2021). "XIST is abnormally expressed in many sexually dimorphic diseases, including autoimmune and neurological diseases, pulmonary arterial hypertension (PAH), and some types of cancers." (PMID 39639337, 2024). "Furthermore, the upregulation of XIST represses expression of Kruppel-like factor 2 (KLF2), encoded on chromosome 19, in female pulmonary arterial endothelial cells, mimicking the repression of KLF2 observed in human pulmonary arterial hypertension." (PMID 34068984, 2021).
pulpitis (2 papers, 2021 to 2023). Inflammation of the dental pulp. "Three lncRNAs (i.e., XIST, MIR155HG, and LINC00630) are identified to be key factors involved in the ceRNA network of pulpitis." (PMID 33777260, 2021).
renal fibrosis (2 papers, 2022 to 2024). A final common manifestation of a wide variety of chronic kidney diseases characterized by glomerulosclerosis and tubulointerstitial fibrosis. "Knockdown of XIST also inhibited apoptosis and inflammation caused by renal fibrosis in mice model by mir-19b mediated downregulation of SOX6, and several studies demonstrated XIST as a potential biomarker for diseases related to glomerular nephropathy." (PMID 40176927, 2024). "Another IncRNA of XIST also showed an up-regulated level in human DN, and this increased expression of XIST is closely related to renal fibrosis." (PMID 36154667, 2022).
systemic sclerosis (2 papers, 2024). A chronic disorder, possibly autoimmune, marked by excessive production of collagen which results in hardening and thickening of body tissues. "The fact that serum reactivity towards antigens of XIST RNP complexes has been identified in patients with SLE and patients with systemic sclerosis (SSc) and dermatomyositis suggests that this is a generalizable mechanism in autoimmune diseases with female predominance." (PMID 38791207, 2024).
amyotrophic lateral sclerosis (1 paper, 2025). Amyotrophic lateral sclerosis (ALS) is a neurodegenerative disease characterized by progressive muscular paralysis reflecting degeneration of motor neurons in the primary motor cortex, corticospinal tracts, brainstem and spinal cord. "Poly (ADP-ribose)-polymerase-1 (PARP1) is another secreted protein that is differentially expressed in XIST-silenced tissues and is activated in MS and different neurodegenerative diseases, including Huntington’s disease and amyotrophic lateral sclerosis." (PMID 40407589, 2025).
asthma (1 paper, 2024). "Results revealed that XIST was a potential genetic biomarker associated with gender differences in asthma prevalence." (PMID 39346946, 2024). "Firstly, it is based on predictive analysis of existing databases to identify gender-specific differences in asthma prevalence genes, suggesting XIST as a potential biomarker." (PMID 39346946, 2024). "Through bioinformatics analysis, it was revealed that XIST is significantly upregulated in pediatric asthma patients." (PMID 39346946, 2024).
autism (1 paper, 2017). Persistent deficits in social interaction and communication and interaction as well as a markedly restricted repertoire of activity and interest as well as repetitive patterns of behavior. "By analyzing 30 ASD females and 35 female controls, increased X chromosome skewness (e.g., >80:20%) was detected in autism group (33%) compared to controls (11%); but no mutation of XIST gene was found in both groups." (PMID 27992373, 2017).
bladder tumors (1 paper, 2021). "XIST can act as an oncogenic lncRNA and induce growth in pancreatic and bladder tumors by interacting and inhibiting miR-124." (PMID 34621163, 2021).
Bovine mastitis (1 paper, 2019). INFLAMMATION of the UDDER in cows. "To explore the potential function of XIST during the process of bovine mastitis, we firstly performed RT‐qPCR analysis to measure the expression level of lncRNA XIST in bovine mammary tissues." (PMID 30362186, 2019). "Considering that XIST was up‐regulated in MAC‐T cells in response to E. coli or S. aureus infection, we wondered whether XIST was involved in the regulation of E. coli or S. aureus‐triggered production of pro‐inflammatory factors through potential mechanisms in bovine mastitis." (PMID 30362186, 2019).
Chagas disease (1 paper, 2022). A parasitic infection caused by Trypanosoma cruzi. "We also found that XIST is one of the tops up-regulated lncRNA in Chagas disease." (PMID 36072583, 2022).